TWIST1 (twist family bHLH transcription factor 1)
Diseases named in the same sentence as TWIST1 in open-access papers (continued):
Sharing a sentence is not in itself a finding about the gene and the disease.
breast carcinoma (continued). "By overexpressing TWIST1, an epithelial to a mesenchymal transition transcription factor, activation of the PDGFRB promoter was observed, which leads to increased proliferation and migration in a breast cancer cell line." (PMID 39365797, 2024). "In cancer, Twist1 promotes angiogenesis, and it has been reported that Twist1 overexpression correlates with an increased expression of the vascular endothelial growth factor (VEGF) and angiopoietin-2 (Ang-2) genes in breast cancer cells." (PMID 38473317, 2024). "Despite inhibiting the proliferation of tumor cells, DOX could also promote wound healing and invasion ability of breast cancer cells by inducing EMT via regulation several factors including TGF-β, NF-kB, Twist1, Snail." (PMID 39544364, 2024). "This study reveals a non-canonical function of the E3 ubiquitin ligase FBXO3 in PI3K-induced breast cancer metastasis, showing that FBXO3 binds to and protects USP4 from aspartyl aminopeptidase (DNPEP)-mediated degradation, resulting in Twist1 protein stabilization and increased tumor metastasis." (PMID 38134227, 2023). "We found that USP13 and Twist1 can form a negative feedback loop to jointly regulate the migration and invasion of breast cancer cells." (PMID 36732432, 2023). "HSPB1 overexpression led to decreased expression of IKβ-α (a negative regulator of NF-κB) and increased expression of NF-κB, p-IKβ-α, and downstream molecules of NF-κB (Twist1, IL6, and Survivin) in breast cancer cells, indicating the potential role of HSPB1 in regulating NF-κB activity." (PMID 37454220, 2023). "At the same time, co-culture of mature adipocytes and breast cancer cells can promote cancer cell growth and mediate EMT by enhancing the expression of MCF7 cell Forkhead Box C2 (FOXC2), twist family bHLH transcription factor 1 (TWIST1), and N- and E-cadherin." (PMID 37666813, 2023). "Azilsartan significantly (p < 0.001) decreased the expression of NF-kB, twist family bHLH transcription factor 1 (TWIST), snail family zinc finger 1 (SNAIL), snail family zinc finger 2 (SLUG) and bcl2 genes, when compared to untreated cells, in MCF-7 and MDA-MB-231 breast cancer cells." (PMID 36431925, 2022). "Since the transcription activity of TWIST1 and SOX2 in ESCs and breast cancer cells can be modulated through their binding to the promoter region, we hypothesized that a similar scenario may happen in ESCC." (PMID 36553636, 2022). "Moreover, the overexpression of TWIST1 accelerates tumor establishment and growth of MCF-7-derived breast cancer and transforms mouse embryonic fibroblasts in cells with high tumorigenic potential." (PMID 35022561, 2022). "Searching for interacting proteins that may regulate TWIST1 by STRING Interaction Network analysis, we discovered a potential link between TWIST1 and SPOP, a less-known E3 ligase in the breast cancer field." (PMID 36115849, 2022). "The results indicate that as a mediator of TWIST1 destabilization, SPOP promotes metastasis of breast cancer cells and may serve as a potential target for personalized therapy and a clinical marker for disease prognosis." (PMID 36115849, 2022). "Interestingly, initial testing with a panel of breast cancer cell lines revealed an inverse correlation between SPOP and TWIST1." (PMID 36115849, 2022). "Similarly, in breast cancer, high expression of SNAI1 and/or TWIST1 in tumor-adjacent tissues has been demonstrated." (PMID 36140779, 2022). "TWIST1 is upregulated and FOXO3a (the forkhead box class O 3a, which belongs to the FOXO subclass of forkhead transcription factors) is downregulated in breast cancer tissues, and overexpression of TWIST1 can reverse the effect of FOXO3a on proliferation, invasion, migration, and EMT." (PMID 34943943, 2021).
breast carcinoma (continued). "For example, promoter hypermethylation of TWIST1 has been observed but has not been directly correlated with gene repression in breast cancer, although the relationship has been established for other cancers." (PMID 34988459, 2021). "It was reported that overexpression of CT45A could induce breast cancer EMT, and thus foster cancer metastasis by upregulating EMT master gene TWIST1." (PMID 34503444, 2021). "In addition, CD44, a hyaluronan receptor, not only interacts with c-Src and Twist1 in the breast cancer cell line, MDA-MB-231, but also increases tyrosine phosphorylation of Twist1 by activating c-Src kinase, which promotes Twist1 nuclear translocation." (PMID 33808323, 2021). "Besides, lncRNA NONHSAT101069 was overexpressed in breast cancer tissues and promoted epirubicin resistance, migration, and invasion of breast cancer cells through regulation of NONHSAT101069/miR-129–5p/Twist1 axis in breast cancer." (PMID 32891166, 2020). "However, since integrin α5 and integrin β1 served as important mesenchymal marker to regulate EMT during breast cancer, the effect of TFPI2-mediated TWIST1 on regulation of integrin β1 also needs to be further investigated." (PMID 32248791, 2020). "Mutual exclusivity data from the n = 1,105 breast cancer TCGA dataset revealed that PAPP-A has a significant tendency towards co-occurrence with mesenchymal markers Vimentin (VIM), SNAI1 (Snail), SNAI2 (Slug), Zeb1, Zeb2 and Twist1." (PMID 32792532, 2020). "Parallel to these, we thought that the nonmalignant mouse breast cancer cell line (67NR) stably expressing glutamic acid mutants of TWIST1 would gain metastatic ability when implanted into the breast tissue of BALB/c mice." (PMID 32922123, 2020). "Quantitative real-time PCR analyses of EMT genes TWIST1, Snail1, Snail2 and CDH2 in monocultured and ASCs co-cultured MCF-7 and MDA-MB-231 revealed that most of these EMT signature genes were downregulated in co-cultured breast cancer cells." (PMID 33271950, 2020). "In addition, hypoxia has been reported to induce the expression of epithelial mesenchymal transition (EMT) genes (TWIST1, SLUG and SNAIL), thus promoting breast cancer’s invasion." (PMID 31952335, 2020). "ARTN was found to promote metastasis and poor survival outcome in patients with estrogen receptor (ER) negative mammary carcinoma (ER‐MC) via its cooperation with twist family BHLH transcription factor 1 (TWIST1)." (PMID 32573073, 2020). "Recently, it was also shown that TWIST1 is phosphorylated by Akt, in turn, TWIST1 transcriptionally upregulates AKT2 gene in breast cancer cells, and this induction leads to invasion and migration of breast cancer cells." (PMID 32922123, 2020). "Li and coworkers reported that pH-sensitive polymeric nanomaterials loaded with siRNAs targeting TWIST1 in combination with paclitaxel suppressed EMT, reducing tumor growth and metastasis as well as ECM degradation in breast cancer cells and orthotopic mice models." (PMID 31861725, 2019). "p-Akt phosphorylates TWIST1 thus contributing to EMT and breast cancer metastasis." (PMID 31331001, 2019). "Here, we found that ectopic expression of Twist1 could induce MMP2 expression and promote breast cancer migration, invasion and lung metastasis." (PMID 30819235, 2019). "In addition, relapse-free survival rates of breast cancers (both HER2+ and HER2−) were negatively correlated with the level of Twist1, but positively correlated with BTG2 expression by open data analysis." (PMID 31138781, 2019).
breast carcinoma (continued). "Furthermore, as MMP2 is the direct downstream target of Twist1, repression of Twist1 resulted in downregulation of MMP2 expression, thereby inhibiting the metastasis of breast cancer cells." (PMID 30819235, 2019). "Whereas, upregulation of RBMS3 could alleviate Twist1-induced MMP2 expression and abrogate migration, metastasis ability of breast cancer cells, correspondingly." (PMID 30819235, 2019). "TWIST1, a known regulator of EMT, is highly phosphorylated on Serine 68 residue in HER2-positive invasive ductal carcinomas, thereby stabilizing the protein and promoting breast cancer invasiveness." (PMID 31075939, 2019). "Overexpression of TBX3 at early pre‐invasive stages (CCL, DCIS) of breast cancer progression, inducing other molecular regulators of EMT (including SLUG and TWIST1), acts as an enabler to set the stage for basement membrane breakdown and invasion into adjacent stroma." (PMID 30697731, 2019). "More breast cancer patients were stage III or IV (39 out of 86, 45.3%) when Twist1 displayed a high expression level, while fewer breast cancer patients were at these stages (7 out of 45, 15.6%) when Twist1 displayed a low expression level (χ2 = 10.239, P = 0.001)." (PMID 30518916, 2018). "Results showed that co-delivery of miR-34a and TQ is able to inactivate EMT signaling pathway by directly targeting TWIST1 and ZEB1 in BT-549 cell line, indicating that they might be a promising therapeutic combination against breast cancer metastasis." (PMID 28423483, 2017). "The same study shows that Twist1 mediates the thrombin induced up-regulation of angiogenesis growth factors and receptor proteins such as VEGF, GRO-α, KDR, Ang-2, MMP-1, and CD31 in both human breast cancer and murine melanoma cell lines." (PMID 28099910, 2017). "LBX1 directly up-regulates ZEB1, ZEB2, Snail and TGFB2 but not Twist1 and promotes breast cancer cell migration, implying a role as a master regulator of EMT." (PMID 26797644, 2016). "Our study revealed a novel mechanism in breast cancer cells that TRIM28 enhances metastasis by stabilizing TWIST1, suggesting that targeting TRIM28 could be an efficacious strategy in breast cancer treatment." (PMID 27412325, 2016). "Methylation-sensitive high-resolution melting was used to screen promoter methylation in a panel of 13 genes reported as methylated in breast cancer (RASSF1A, TWIST1, APC, WIF1, MGMT, MAL, CDH13, RARβ, BRCA1, CDH1, CDKN2A, TP73, and GSTP1) in 29 tumour pairs (16 ipsilateral and 13 contralateral)." (PMID 26452468, 2015). "Because both Twist1 and HMGA2 can regulate the proteins responsible for ECM degradation, we speculated that miR-33b may regulate migration and invasion in breast cancer cells via matrix remodeling." (PMID 25919570, 2015). "TWIST1 has also been shown to be overexpressed in numerous solid tumors, including aggressive and metastatic forms of breast cancer; however, it is not expressed in normal adult tissues." (PMID 25759817, 2015). "In summary, we find that miR-129-5p suppresses breast cancer development and progression and that down-regulation of miR-129-5p, through a Twist1-Snail negative feedback loop, is required for EMT initiation and maintenance." (PMID 26460733, 2015). "Moreover, miR-33b can reduce the stemness and inhibit the metastasis of breast cancer cells to the lungs through the regulation of HMGA2, SALL4 and Twist1." (PMID 26146543, 2015). "We observed lack of correlation between CTCs and expression of TWIST1 and SLUG in breast cancer cells or cancer associated stroma." (PMID 26194471, 2015). "Our results demonstrate that BRMS1 attenuates TGF-β1-induced breast cancer cell invasion through inhibition of NF-κB and subsequent reduction of HIF-1α expression required for Snail and TWIST1 expression, uncovers a new mechanism through which BRMS1 suppresses breast cancer progression." (PMID 26520789, 2015).
breast carcinoma (continued). "We observed a lack of association between CTCs and expression of TWIST1 and SLUG in breast cancer cells or cancer associated stroma." (PMID 26194471, 2015). "Interestingly, Twist1, which has been reported as a link between EMT and stemness in breast carcinomas, is expressed in disseminated breast cancer cells that persist in the bone marrow after chemotherapy." (PMID 25019555, 2014). "These authors also showed that co-culture of human MDA-MB-231 breast cancer cells with murine astrocytes protected the cancer cells from apoptosis by vincristine through upregulation of the anti-apoptotic survival genes, BCL2L1, TWIST1, and GSTA5." (PMID 25566497, 2014). "For example, Twist1 was found to act upstream from Snail and induce EMT-like transformation in a mouse xenograft model with human breast cancer; while a comparison of benign and malignant pheochromocytoma suggested that Snail target on Twist promoting malignant transformation." (PMID 23378237, 2013). "Also increased expression of TWIST1 and SNAI1 in lymph node metastasis (LNM) of early breast cancer patients, reported previously by our group, conferred worse prognosis, confirming the correlation of EMT with aggressive disease behavior." (PMID 24217115, 2013). "Furthermore, LLL12 inhibited Twist1, Notch-1, and Notch-3 expression in ALDH+ breast cancer stem-like cells, which have recently been reported as STAT3 or Interleukin-6 target genes." (PMID 24376586, 2013). "For example, TWIST1 and RARB methylation was used to detect breast cancer cells in ductal lavages." (PMID 22570110, 2012). "Multivariate analysis of the association of tumor ARTEMIN (ARTN) and TWIST1 expression with five-year relapse free (RFS) and overall survival (OS) in patients with estrogen receptor (ER) negative mammary carcinoma (ER-MC)." (PMID 22060274, 2011). "Correlation between ARTEMIN (ARTN) and TWIST1 expression in estrogen receptor (ER) negative mammary carcinoma (ER-MC)." (PMID 22060274, 2011). "Another mammary carcinoma subtype that has recently been delineated, termed claudin-low, exhibits high expression of genes involved in epithelial-mesenchymal transition (EMT), such as SNAI1 and TWIST1, and cancer stem cell-like features." (PMID 22060274, 2011). "For breast cancer, some of the genes reported to undergo hypermethylation are involved in evasion of apoptosis (DAPK, TWIST1, HOXA5), cell cycle regulation (p16, CCND2), cell invasion and metastasis (CDH1, APC), DNA repair (BRCA1) and cell signaling (ER and RARβ2)." (PMID 20226036, 2010). "A separate study suggested that Twist1 downregulates the expression of FOXA1 to increase the level of choline kinase in estrogen receptor-negative breast cancer cell lines, thus providing environmental advantages for cancer cells and promoting the metastasis of breast cancer." (PMID 40003882, 2025). "We previously reported that TWIST1 induces the transcriptional activation of mesenchymal genes such as VIM (Vimentin) and SNAI2 (Snail 2) but induces the transcriptional repression of epithelial genes such as CDH1 (E-cadherin) and ESR1 (ERα) in breast cancer cells." (PMID 38893094, 2024). "Interestingly, TWIST1 expression is correlated with high-level PD-L1 expression in ERα-negative breast cancer cells." (PMID 38893094, 2024). "However, how TWIST1, a master EMT-inducing transcription factor, regulates PD-L1 expression and breast cancer immune escape is still unknown." (PMID 38893094, 2024). "In breast cancer cells, reduced expression of the circadian gene PER2 was found to correlate with increased expression of the pro-EMT genes Snail Family Transcriptional Repressor 2 (SLUG), Snail Family Transcriptional Repressor 1 (SNAI1), and Twist-related protein 1 (TWIST1)." (PMID 38173841, 2023).
breast carcinoma (continued). "The currently postulated mechanisms explaining the role of RBMS3 in the progression of breast cancer include involvement in the epithelial–mesenchymal transition (EMT) by inhibiting the Wnt/β-catenin signaling pathway and other EMT-related transcription factors, such as TWIST1 or PRRX1." (PMID 36769184, 2023). "Therefore, targeting ER and Twist1 pathway at the same time may be enough to inhibit AGR2 and improve the survival rate of breast cancer patients." (PMID 37197416, 2023). "One study showed that TWIST1 binds to the promoter of CD24 and transcriptionally regulates CD24 expression, resulting in stem cell traits such as self-renewal and the ability to form mammospheres in breast cancer, suggesting that EMT-TFs are mainly involved in the BCSC phenotype." (PMID 35743249, 2022). "Interestingly, TWIST1, a transcription factor that plays a pivotal role in metastasis by promoting epithelial-mesenchymal transition (EMT) was part of the gene expression signature previously identified in DTC of breast cancer patients." (PMID 35158902, 2022). "TWIST1 and TWIST2 have previously been described as playing a distinct role during embryonic development and having anti-correlated transcriptional expression patterns in spontaneous focal mammary tumors in mice and in human melanoma, colon, kidney, lung, and breast cancer." (PMID 35022561, 2022). "Moreover, studies on ovarian and breast cancer revealed that OPN could promote the expression of HIF-1α in a PI3k/AKT pathway-dependent manner and then regulate TWIST1 gene to monitor EMT." (PMID 34070192, 2021). "Notch can directly induce Slug, but not Snail and TWIST1, in breast cancer cell lines." (PMID 32322559, 2020). "The human breast cancer PCR array detected significantly increased expression of SLIT2 (slit guidance ligand 2) and decreased expression of IGF1 (insulin-like growth factor 1) and TWIST1 (twist family BHLH transcription factor 1) with 3-fold changes in the expression levels." (PMID 32565805, 2020). "Since alanine mutants could not be phosphorylated, we thought that the malignant mouse breast cancer cell line (4T1) stably expressing alanine mutants of TWIST1 would lose metastatic ability when implanted into the breast tissue of BALB/c mice." (PMID 32922123, 2020). "Taken together, our results show that Akt-mediated phosphorylation of TWIST1 can revert the nonmetastatic phenotype of breast cancer cells into metastatic phenotype and changes in expression of vimentin and N-cadherin may not be enough to explain EMT." (PMID 32922123, 2020). "In human breast cancer, NF-κB activation increased transcriptional activation of EMT regulator gene expression by binding directly to the sites of EMT transcription factors, including SNAIL1, SLUG, TWIST1 and SIP1 promoter, which promotes an aggressive phenotype of breast cancer cells." (PMID 31126310, 2019). "Importantly, we describe for the first time the ability of melatonin to downregulate TWIST1 (Twist-related protein 1) in estrogen-dependent but not in estrogen-independent breast cancer cells." (PMID 31331001, 2019). "We conclude that removal of a single EMT‐TF, ZEB1, from an established mesenchymal breast cancer cell, is not sufficient to revert the tumor cells into a more epithelial phenotype, as we also demonstrated for Snail1 and Twist1 in an independent breast cancer model." (PMID 29744893, 2018). "Disrupting the interaction of BRD4 with Twist1 by using BET-specific inhibitors (such as JQ1) may be a novel approach to indirectly suppress Twist1 function and provide a potential new target for the treatment of basal-like breast cancer." (PMID 28099910, 2017).